LOX (lysyl oxidase)
Diseases named in the same sentence as LOX in open-access papers (continued):
Sharing a sentence is not in itself a finding about the gene and the disease.
tumor (continued). "In previous studies, the expression of LOX was usually stronger at the tumor invasive front than in the tumor center in OSCC, and higher expression of LOX was associated with advanced pathological grade." (PMID 34930321, 2021). "In cancer research, LOX has received considerable attention, both owing to tumour growth and invasion-promoting properties on the one hand and to tumour suppressor functions on the other hand." (PMID 34095157, 2021). "In particular, elevated lysyl oxidase (LOX) expression by the primary tumor cells increases collagen crosslinking, leading to tissue fibrosis, and triggers pro-survival and proliferation signaling in other cancer cells." (PMID 33805737, 2021). "This is an aminomethylenethiophene (AMT) based inhibitor, which helped to elucidate the mechanisms by which LOX drives tumor progression." (PMID 33669630, 2021). "LOX is a secreted extracellular matrix protein that plays an important role in remodeling the extracellular matrix and promoting tumor progression." (PMID 35126449, 2021). "A similar phenomenon was also detected in cell proliferation, in which downregulating of LOX inhibited cell growth and tumor formation both in vivo and in vitro." (PMID 34583752, 2021). "Taken together, this study suggests that RT-R-MDA-MB-231 cells derived from highly metastatic TNBCs increase HIF-1α expression, leading to secretion of LOX, which contributes to tumor progression by enhancing premetastatic niche formation." (PMID 33126606, 2020). "Then, we generated organoid cultures of this doxorubicin-resistant PDX tumor and demonstrated that combination of LOX inhibitor with doxorubicin significantly decreased organoid size compared to single agent treatments after 9 days of treatment." (PMID 32415208, 2020). "Tumor cell-related functions of LOX have emerged, however, within signaling frameworks, and brief summaries are provided in the relevant contexts." (PMID 32708046, 2020). "It is noteworthy that in vitro experiments with LOXs inhibitors showed a prominent role of LOXL-2 versus LOX in tumor growth, collagen cross-linking, angiogenesis, and fibroblast activation." (PMID 31650200, 2020). "Lysyl oxidase-mediated collagen crosslinking then increases the stiffness of the tumor tissue and activates pro-proliferative β1-integrin signaling." (PMID 33014869, 2020). "Using the previous approach, we found a significant increase in CA9 and LOX expression in tumor tissue, which was significantly more pronounced in CD68High patients." (PMID 32231135, 2020). "Contrasting these observations, LOX was reported to have tumour suppressive effects in human OSA cell lines, although this capacity was not tested in vivo." (PMID 33066583, 2020). "The protein levels of VEGF, MMP9, MMP2 and LOX increased in the sera of CT26‐P2X7R tumour‐bearing mice compared with those of CT26‐Con mice." (PMID 32735377, 2020). "Meanwhile, overexpression of LOX in tumor initiating cells (TICs)-enriched HCC enhances tube formation of endothelial cells through secreted VEGF, wherein the stimulated angiogenesis can be blocked by LOX inhibitor β-aminopropionitrile." (PMID 33371259, 2020). "β-aminopropionitrile (BAPN), the inhibitor of the ECM crosslinking enzyme lysyl oxidase, promotes tumor latency and inhibits tumor growth." (PMID 33050609, 2020). "We found higher levels of COL1A1 and LOX in tumor tissues compared with NTs, which resulted in more significant paired tissues." (PMID 31906302, 2020). "LOX also alters the endosteal niche by activating the osteoclasts, thus preparing a permissive environment for circulating tumor cells to colonize the bone." (PMID 32232008, 2020). "LOX was reported to promote tumor progression and distant metastasis via enhancing matrix stiffness in KIRC." (PMID 32970930, 2020). "Previous studies have reported that LOX is a tumour suppressor, the expression of which was found to be reduced in the tumour tissue, and its downregulation was controlled through methylation." (PMID 32912229, 2020).
tumor (continued). "Mice bearing RT-R-MDA-MB-231 xenografts expressed a significantly higher level of HIF-1α in tumor tissue and significantly increased plasma LOX levels compared to those with MDA-MB-231 cells." (PMID 33126606, 2020). "Matrix metalloproteinases (MMPs), heparanase, cathepsins, urokinase plasminogen activator, and lysyl oxidase are ECM modifying enzymes contributing with tumor metastasis." (PMID 32467737, 2020). "Hypoxia inducible factor-1α (HIF-1α) induced in the tumor microenvironment leads to the release of lysyl oxidase (LOX), which mediates collagen crosslinking at distant sites to facilitate environmental changes that allow cancer cells to easily metastasize." (PMID 33126606, 2020). "NDGA impacts metastasis of tumor cells through LOX inhibition but also due to down-regulation of neuropilin 1, a single-pass transmembrane protein that functions as a “signaling platform” on the cell surface." (PMID 32184727, 2020). "In particular, loss of LKB1, which occurs in 34% of adenocarcinoma and 19% of squamous carcinomas, induces mTOR-HIF1α signaling to induce lysyl oxidase expression within the tumor microenvironment." (PMID 33014869, 2020). "Upon stimulation by TGF-B in the tumor microenvironment, these CAFs were found to secrete lysyl oxidase (LOX), which facilitates tumor growth and progression." (PMID 32268527, 2020). "Most of the anti-tumor effects of NDGA are supported by its inhibitory action on LOX enzymes and other inflammatory pathways as well as inhibition of receptor tyrosine kinase signaling pathways." (PMID 32184727, 2020). "For example, hypoxia-induced LOX expressed by the primary tumour acts at the metastatic site, where it cross-links collagen IV, which provides the adhesion for bone marrow-derived cells, as shown in breast cancer." (PMID 33037194, 2020). "LOX proteins also regulate development, senescence, tumor suppression, cellular growth, and chemotaxis." (PMID 32621591, 2020). "The secretion of lysyl oxidase (LOX) by tumor cells in response to intratumoral hypoxia, or as a wound healing response to surgery, can increase the systemic LOX activity, thereby catalyzing collagen crosslinking at distant sites, including within the lung." (PMID 33014869, 2020). "In vivo testing also showed a significant decrease in tumor growth upon combination therapy in this chemoresistant PDX model expressing LOX." (PMID 32415208, 2020). "LOXs showed variability of expression during tumor development, with the possibility of exerting either promotion or even inhibition effects depending on the type of LOX expressed, the tumor type, and the microenvironment." (PMID 31650200, 2020). "LOX is a major contributor to the stiffness of the tumor stroma, as it up-regulates cross-linking of collagen fibers as well as cross-linking of collagen and other ECM components." (PMID 32434573, 2020). "The role of hypoxia-induced lysyl oxidase (LOX) on the tumor microenvironment and chemoresistance has been targeted using stable exogenous re-expression of miR-142-5p." (PMID 33255471, 2020). "In turn, tumor cells regulate immune cell functions such as the production of inflammatory enzymes (COX and LOX), matrix metalloproteases, and chemokines to modulate tumor metastasis." (PMID 31979409, 2020). "Inhibiting LOX in combination with doxorubicin as a first-line therapy led to a stronger delay in tumor growth as compared to individual treatments." (PMID 32415208, 2020). "Vice versa, inhibition of lysyl oxidase, a matrix cross-linking enzyme involved in tumor stiffening, was shown to reduce the tumor stiffness and tumor vasculature in a mouse mammary tumor model." (PMID 33614496, 2020). "The mode of catalytic activity is believed to be consistent in all LOX and LOXL proteins, and accumulating studies have shown that LOX activity plays important roles in tumor invasion and metastasis." (PMID 30704479, 2019).
tumor (continued). "miR-200b and miR-30a are validated regulators of LOX, and both of them are able to decrease invasiveness of tumor cells by the inhibition of LOX." (PMID 31752264, 2019). "In this review, we have described how LOX proteins modulate the tumor microenvironment and how these changes are integrated by IACs to modulate cell behavior." (PMID 31130685, 2019). "The deposition and remodeling of ECM components, including fibronectin, periostin, tenascin-C, collagen IV and lysyl oxidase (LOX) are key processes in the development of the pre-metastatic niche and have been shown to occur before the arrival of tumor cells." (PMID 30847298, 2019). "Although LOX pro-peptide displays tumor suppressor activity, LOX family oxidases support metastasis." (PMID 31121900, 2019). "Hypoxia within the primary tumor influences a wide variety of processes, including the increased expression of lysyl oxidase (LOX)." (PMID 31071959, 2019). "Targeting tumor stiffness via the inhibition of LOX enzymatic activity has been demonstrated to decrease metastatic dissemination of breast and colorectal tumor cells in vivo." (PMID 31067787, 2019). "This suggests that ATP7A plays a key role in the activation of LOX proteins whose activities promote tumor progression and metastasis." (PMID 31540259, 2019). "Tamoxifen tunes the balance between cross‐linking (LOX) and degrading enzymes (MMPs) secreted by PSCs to modulate collagen and fibronectin fiber architecture in the tumor microenvironment." (PMID 30538116, 2019). "A subsequent study evidenced that LOX expression and activity are sharply higher in tumor endothelial cells than in normal cells and that LOX knockdown limits tumor endothelial cell motility and tubulogenesis through the inhibition of FAK signaling." (PMID 31615160, 2019). "LOX activity has been reported to regulate tumor cell behaviors by oxidizing lysine residues of their substrates to produce hydrogen peroxide, and it has recently been shown that the presence of hydrogen peroxide can facilitate Src activation." (PMID 30704479, 2019). "Compared with the control group, the tumor tissues from mice in the LOX inhibition group had reduced relative expression levels and enzyme activities of MMP-2 and MMP-9 (P < 0.05)." (PMID 31777578, 2019). "In a rat model of prostate cancer, LOX inhibition seems to have context-dependent effects during different stages of tumor progression." (PMID 31106200, 2019). "Inhibition of LOX led to stromal depletion and promoted tumor infiltration by drugs and immune cells." (PMID 30796212, 2019). "Matrix stiffness can be made stiffer upon cross-linkages among collagen fibers by LOX, one of products secreted by tumor cells that are under hypoxic conditions." (PMID 31861892, 2019). "In vivo PET imaging after injection of this tracer demonstrated much higher tumor uptake in PD-L1-positive LOX tumor-bearing mice than in PD-L1-negative SUDHL6-xenografted mice (7:1%ID/g ratio at 90 min p.i.)." (PMID 31394799, 2019). "At the same time, metastasized and newly formed tumor cells require LOX to construct new ECM and interact with the surrounding environment after they have reached neighboring or distal tissues, so that these cells can colonize these sites." (PMID 31777578, 2019). "This review article summarizes the main findings on the role of LOX proteins in modulating the tumor microenvironment, with a particular focus on how ECM changes are integrated by IACs to modulate cells behavior." (PMID 31130685, 2019). "Tumor-derived LOX drives angiogenesis through PDGFRβ stimulation and AKT activation leading to an increased production of VEGF." (PMID 31615160, 2019). "While LOXL2 has been involved in the angiogenic response of both normal and tumoral endothelial cells, evidence regarding the contribution of LOX to neovascularization is weak and the studies were mainly focused on tumor angiogenesis." (PMID 31615160, 2019).
tumor (continued). "In NSCLC, high LOX expression is associated with invasion and poor prognosis, and targeting the LOX pathway in tumor cells inhibits metastasis." (PMID 31121900, 2019). "A dual role of LOX in tumorigenesis has been proposed, as they can be involved in both neoplastic transformation and tumor suppression." (PMID 31467634, 2019). "The involvement of LOX in the remodelling of stromal collagen and subsequent changes to the biomechanical properties of the tumour microenvironment has been well established." (PMID 31117256, 2019). "In the next two paragraphs, we will describe how changes in ECM stiffness are detected by integrins to regulate both LOX expression and cancer cell proliferation and invasion, generating a positive-feedback loop that strongly supports tumor progression." (PMID 31130685, 2019). "The role of LOX in mediating biomechanical changes at the tumour microenvironment is well established." (PMID 31117256, 2019). "Erler and colleagues showed that hypoxia in the primary tumor can induce the secretion of lysyl oxidase (LOX) resulting in collagen cross-linking and ECM remodeling at distant sites that favor recruitment of BMDCs and eventual metastatic seeding." (PMID 30767150, 2019). "It must be pointed out that LOX was also known as Ras recision gene, a tumour suppressor, the expression of which is deeply altered in tumour tissues." (PMID 30650583, 2019). "Overexpression of lysyl oxidase and its involvement in tumor progression and metastasis were shown in various cancers." (PMID 31467634, 2019). "The ability of LOX to remodel the extracellular matrix promotes tumor cell migration and adhesion via the activation of focal adhesion kinase (FAK1)." (PMID 31540259, 2019). "We found that the expression and enzyme activity levels of MMP-2 and MMP-9 were decreased in mouse tumor tissues after LOX inhibition." (PMID 31777578, 2019). "After intravenous injection of LOX-1RNAi cells, we found that LOX-1 silencing influences both the engraftment of the tumor and the metastasis development, acting by angiogenesis." (PMID 31608230, 2019). "Studies have shown that LOX secreted from hypoxic primary tumor cells accumulates in the pre-metastatic sites; LOX is an indispensable factor for recruiting bone marrow-derived CD11b+ cells (i.e., immature myeloid progenitor cells) to metastatic sites." (PMID 29848296, 2018). "We also monitored the expression level of tumor cell-secreted LOX, MMP-2 and VEGFA, and the bone marrow-derived CD11b+ cell number in the distant organs in the in vivo model." (PMID 29848296, 2018). "Direct inhibition of LOX yields reduced tumor size and stiffness, resulting in a delay in tumor progression." (PMID 29881724, 2018). "The in vivo effects of tumour secreted LOX on pre-metastatic bone lesion formation were preventable if mice were simultaneously treated with the potent bisphosphonate Zoledronic acid to prevent bone lesion formation." (PMID 29098360, 2018). "LOX also reportedly improved tumor cell proliferation and survival through focal adhesion kinase (FAK) activation, which subsequently upregulates fibronectin and provides a permissive niche to support metastasis." (PMID 29732010, 2018). "Accumulating evidence suggests that LOX induces cancer progression by mediating a variety of steps in tumor metastasis." (PMID 29472856, 2018). "The potential role of LOX as the tumor suppressor has been described for example in colon, pancreatic, basal and squamous cell carcinomas." (PMID 30583585, 2018). "LOX(L) inhibition by itself affected tumor growth in the five tested models very differently, which has significant implication for the clinical use of LOX(L) inhibitors as auxilliary agents." (PMID 29780168, 2018). "Histological analysis of femora from mice carrying 4T1 LOX secreting tumours revealed a reduction in osteoblast numbers concomitantly with an increase in osteoclast numbers, an effect that was abrogated by shRNA LOX knockdown in the primary tumour." (PMID 29098360, 2018).
tumor (continued). "We previously showed that patients with high LOX expressing ER− tumours exhibit significantly worse distant metastasis-free survival and poorer overall survival than low LOX expressing ER− counterparts." (PMID 29098360, 2018). "Stiffening of the PDAC tumor stroma is achieved by the cross-linking of collagen fibers by lysyl oxidase (LOX), an extracellular amine oxidase that predominantly cross-links collagen I." (PMID 30200666, 2018). "Of note, IR promotes secretion of LOX from several tumor cell lines in a time- and dose-dependent manner." (PMID 30105016, 2018). "Multicellular tumor spheroids (MCTS) generated from LOX or LOXL2 overexpressing 4T1 cells were reduced in size." (PMID 29780168, 2018). "LOX has also been found to function as a tumor suppressor in basal and squamous cell carcinoma, gastric cancer, and osteosarcoma cells, but as a tumor promoter in colorectal cancer, esophageal squamous cell carcinoma, lung adenocarcinoma, and laryngeal cancer." (PMID 30701028, 2018). "Desmoplastic reaction induces tumor stiffness via processes closely attributed to the over-activation of lysyl oxidase (LOX), an enzyme that crosslinks collagen and other ECM components." (PMID 29883428, 2018). "Regarding the literature data, the role of LOX in cancer seems to be dual, since both down- and upregulation of LOX in cancer cell lines and tumor tissues has been described." (PMID 30583585, 2018). "Our data thus suggest that the inactive pro-LOX acts as major tumor suppressor, in addition to the previously known LOX-PP." (PMID 30701028, 2018). "Increasing tumor cross-linking is directly related to increases in tumor stiffness, thus LOX is a key factor found in tumor progression." (PMID 29881724, 2018). "These tumor permeation studies demonstrated that in the LOX/LOXL2 OE tumors only few cell layers surrounding the blood vessels are well supplied with H33342 and that small molecules barely permeate into the dense surrounding tissue." (PMID 29780168, 2018). "Previous studies have reported a solid and consistent anti-tumor effect of LOX(L) inhibition in a variety of different tumor models." (PMID 29780168, 2018). "Considering the upregulation of LOX during tumor hypoxia, reductively activatable prodrugs of βAPN have been developed, which were shown to be capable of inhibiting the invasion of MDA-MB-231 breast tumor cells under hypoxic conditions in vitro." (PMID 29755969, 2018). "We and others have shown that the HIF/LOX pathway played an important role in tumor microenvironment formation in breast and liver models." (PMID 29799025, 2018). "In this regard, our results elucidated a new pathway of the EGFR signaling and suggested the potential therapeutic target of LOX for the treatment in tumor metastasis." (PMID 29472856, 2018). "The panel of IRF-1-induced genes also includes those encoding caspases, tumor necrosis factor-related apoptosis-inducing ligand (TRAIL), and lysyl oxidase (LOX), the latter of which has also been identified as a tumor suppressor." (PMID 29599126, 2018). "ECM isolates from all tumor models showed improved permeability for DOX after lysyl oxidase inhibition." (PMID 29780168, 2018). "In contrast, increased LOX secretion in the same tumour type drives matrix stiffening through collagen crosslinking, hereby enabling tumour cell dissemination and metastasis." (PMID 29953488, 2018). "LOX, secreted by primary tumour cells, is responsible for catalysing the cross-linking of both collagen and elastin, which in turn increases matrix stiffness and total adjacent ECM volume." (PMID 30287763, 2018). "In all these studies, higher expression of LOX has been correlated with tumor grade, invasion and migration of cancer cells, increased metastatic disease, and decreased survival." (PMID 30583585, 2018). "Lysyl oxidase-mediated tumor uptake was proven by pharmacological inhibition using β-aminopropionitrile and by employing negative-control analogs of impeded or abolished targeting capability." (PMID 29755969, 2018).